VIM (vimentin)
Diseases named in the same sentence as VIM in open-access papers (continued):
Sharing a sentence is not in itself a finding about the gene and the disease.
ovarian carcinoma (continued). "The expression of CK7, additional expression of vimentin, and clinical and histopathological findings enabled us to confirm that six cell lines had been established from primary ovarian cancers." (PMID 9328139, 1997). "Ovarian cancer cell lines, in contrast to the colon cancer cell lines, are positive for the expression of cytokeratin (CK) 7 and for vimentin." (PMID 7510115, 1994). "Flow cytometry and western blot analysis suggested the enhanced stemness of ovarian cancer induced by KLF5 overexpression could be rescued following Vimentin knockdown." (PMID 40307891, 2025). "Conversely, the diminished stemness of ovarian cancer resulting from KLF5 knockdown could be rescued following Vimentin overexpression." (PMID 40307891, 2025). "During epithelial-to-mesenchymal transition (EMT) in ovarian carcinoma, there is downregulation of E-cadherin expression which is located at cell adherent junctions, upregulation of N-cadherin expression and upregulation in the mesenchymal marker of vimentin." (PMID 39974724, 2025). "Moreover, VIM expression was inversely correlated to MPZL3 expression in TCGA ovarian cancer specimens, indicating that decreased MPZL3 expression is associated with upregulation of the canonical EMT gene VIM in ovarian cancer." (PMID 40631617, 2025). "Similarly, overexpression of PGRN in ovarian cancer also accompanied with increased vimentin expression and decreased E-cadherin expression, resulting in cell migration and invasion." (PMID 37660003, 2023). "Vimentin has been found in pancreatic, breast, colon, and ovarian cancers." (PMID 37528887, 2023). "In addition, in-depth single-cell phenotypic characterization of high-grade serious ovarian cancer has shown that cancer cells co-express E-cadherin and vimentin, which correlates significantly with tumor recurrence and metastasis." (PMID 32117780, 2020). "The inhibition of vimentin by FiVe1 significantly sensitized ovarian cancer cells to cisplatin." (PMID 32466394, 2020). "In fact, recent identification of several proteins overexpressed in both PCOS and ovarian cancer, including calreticulin, fibrinogen, superoxide dismutase, and vimentin gave us a clue on the two diseases and even promising subgroup identification of ovarian cancer based on PCOS development." (PMID 32639550, 2020). "The inhibition of vimentin with FiVe1 resulted in a significant sensitization of A2780 and A2780cis cells to cisplatin, revealing new possibilities for improving the chemosensitivity of ovarian cancer cells." (PMID 32466394, 2020). "Our results show, for the first time, that the pharmacological inhibition of vimentin with FiVe1 may be a valuable approach for specifically enhancing sensitivity and tackling cisplatin resistance in ovarian cancer cells." (PMID 32466394, 2020). "However, recently, high VIM expression was also correlated with a prolonged survival in endometrioid cancer patients and better prognosis in ovarian cancer patients." (PMID 31552188, 2019). "In ovarian cancer cells down-regulation of VIM expression resulted in resistance to cisplatin by potentially down-regulating its import and up-regulating its export, indicating that it might also be contributing to cisplatin resistance in the LAR subtype." (PMID 31684899, 2019). "Given that lower E-cadherin but higher Vimentin and Twist expression are hallmarks of EMT process in cancer our data indicated that up-regulated TRPM7 expression was associated with the EMT process of ovarian cancer." (PMID 30819230, 2019). "Induction of EMT by TET is mediated by demethylation of Vimentin promoter in ovarian carcinoma." (PMID 31608277, 2019). "Thus, E-Cadherin, P-Cadherin, Zeb1, HMGA2, Rab25, CD24, NCAM (CD56), Sox11 and Vimentin expression was assessed in 100 advanced-stage ovarian cancer patients undergoing platinum-based chemotherapy." (PMID 29389895, 2018).
ovarian carcinoma (continued). "In addition, SIRT6-mediated invasiveness of ovarian cancer cells was associated with the expression of EMT signaling molecules such as E-cadherin, N-cadherin, snail, vimentin, and active β-catenin." (PMID 30524965, 2018). "A recent report showed that 188Re-liposome could induce E-cadherin and suppress vimentin in human ovarian cancer cells." (PMID 30393570, 2018). "Ectopically expressed linc-ROR promoted proliferation in vitro and in vivo, contributed to cell migration and invasion, and inhibited the epithelial marker E-cadherin, while stimulating expression of the mesenchymal marker vimentin in an ovarian cancer cell line." (PMID 29050257, 2017). "The aim of this study was to focus on in situ morphological changes in the ovarian surface epithelium of tumor tissue in women with epithelial ovarian cancer after we applied the antibodies for markers of EMT vimentin and pluripotency-related markers NANOG, SOX2 and SSEA-4." (PMID 28231820, 2017). "Recently a number of proteins overexpressed in both PCOS and ovarian cancer, such as superoxide dismutase, fibrinogen γ, vimentin, calreticulin, malate dehydrogenase, and lamin B2, have been identified, revealing subgroups of women with PCOS and with an increased risk of developing this malignancy." (PMID 27725832, 2016). "Using an unbiased approach based on principal component analysis of qPCR markers of mesenchymal and epithelial status, we found that CD44v8-10 correlates with epithelial markers such as E-cadherin and EpCAM, while CD44s correlates with mesenchymal markers such as vimentin in ovarian cancer." (PMID 27253518, 2016). "However, relatively little is known about the effects of vimentin expression on drug resistance in ovarian cancer cells." (PMID 27322682, 2016). "Vimentin is a potential therapeutic target for treatment of resistance ovarian cancers." (PMID 27322682, 2016). "Identification of a number of proteins overexpressed in both PCOS and ovarian cancer, such as superoxide dismutase, calreticulin, vimentin, fibrinogen γ, lamin B2, and malate dehydrogenase, assured the identification of women with PCOS with an increased risk of developing this malignancy." (PMID 27725832, 2016). "Such a hybrid stage was described in human ovarian cancer cells freshly isolated from mouse xenografts, or, in situ, in human biopsies in which cancer cells simultaneously express the epithelial marker EpCAM and the mesenchymal marker vimentin." (PMID 26405433, 2015). "Western blot analysis was performed to detect the differences in the expression of the EMT markers, E-cadherin, β-catenin, N-cadherin, vimentin and fibronectin, between human ovarian cancer stem cells and the human epithelial ovarian carcinoma cell line, HO-8910." (PMID 24959289, 2014). "Our spheroid cells also gained expression of human ACTC1 (αSMA) and VIM (Vimentin) mesenchymal markers, similar to ovarian cancer cell-formed spheroids, and doxorubicin-selected MCF-7/ADR cells indicating that an EMT had occurred during cancer progression of the CICs." (PMID 22284662, 2012). "Our study in ovarian cancer epithelial cells consistently showed that MECOM loss, as well as JIB-04 treatment, downregulated ZEB1 along with its non-canonical targets, N-cadherin and vimentin, suggesting potential transcriptional regulation of N-cadherin and vimentin." (PMID 40664642, 2025). "Transient introduction of miR-205 mimics into SKOV3 cell-derived exosomes resulted in enhanced ovarian cancer cell proliferation, migration and invasion, attenuated ovarian cancer cell apoptosis, downregulation of epithelial-mesenchymal transition protein E-cadherin, and elevated Vimentin." (PMID 36439168, 2022). "Our results demonstrated that the SMYD3/ITGB6/TGFβ1-Smad3 positive feedback loop could promote the invasion and adhesion of ovarian cancer spheroids by upregulating the expression of N-cadherin, Snail, and Vimentin and downregulating the expression of E-cadherin." (PMID 34621667, 2021).
ovarian carcinoma (continued). "Therefore, SMYD3 and ITGB6 could stimulate the TGFβ1/Smad3 pathway and regulate the expression of N-cadherin, Snail, Vimentin, E-cadherin in ovarian cancer spheroids and promote the EMT process." (PMID 34621667, 2021). "Indeed, similar to the normal ovarian surface epithelial (OSE) cells previously shown to display both epithelial and mesenchymal characteristics and a remarkable phenotypic plasticity during post-ovulatory repair, double positive E-cadherin and vimentin cells have been observed in ovarian cancers." (PMID 31614568, 2019). "Overexpression of vimentin in A2780-DR cells markedly increased their sensitivity to cisplatin, whereas knockdown of vimentin in A2780, HO-8910-PM and HO-8910 cells increased the resistance to cisplatin, demonstrating that vimentin silencing enhanced cisplatin resistance in ovarian cancer cells." (PMID 27322682, 2016). "Conversely, the expression of N-cadherin, vimentin and fibronectin in ovarian cancer stem cells was 0.698±0.012, 0.839±0.021 and 0.847±0.022, respectively; significantly higher than that in HO-8910 cells (0.228±0.022 for N-cadherin, 0.353±0.027 for vimentin and 0.322±0.019 for fibronectin; P<0.05)." (PMID 24959289, 2014). "OC-MQs increased mesenchymal markers’ expression, including SNAI1, CDH2, FN, VIM, and ZEB1, in ovarian cancer cells." (PMID 39937005, 2025). "We knocked down AP3S1 in ovarian cancer cells and observed a decrease in the protein levels of TGF-β, phosphorylated SMAD2/3 (p-SMAD2/3), vimentin (VIM), and N-cadherin, whereas E-cadherin levels were increased." (PMID 38609993, 2024). "In previous studies, we also found that TMEFF1 promotes the expression of N-cadherin, Vimentin, MMP2, and MMP9 in ovarian cancer cells, inhibits the expression of E-cadherin, and participates in the EMT process." (PMID 38468232, 2024). "The results demonstrated that melatonin inhibited the invasion and migration abilities of ovarian cancer SKOV3 cells while up-regulating E-cadherin expression and down-regulating MMP-9, vimentin, and VEGF protein expressions." (PMID 38751791, 2024). "PCBP1 promotes ovarian cancer migration and invasion in vitro by inhibiting TRIM56 translation, reducing its protein levels, thereby inducing Vimentin expression." (PMID 36902478, 2023). "Upon treating ovarian cancer cells with BPA, a previous study observed that mRNA expression and protein levels of vimentin and snail, two protein families involved in the EMT, were increased." (PMID 37718377, 2023). "In ovarian cancer cells, E3 ubiquitin ligase TRIM56 induced the multi-ubiquitin-mediated proteasome degradation of vimentin, leading to reduced cell migration and invasion." (PMID 36631457, 2023). "The relationship between CoCl2 exposure (HIF-1α inducer) and the expression of vimentin, epithelial cell adhesion molecule (EpCAM), and the growth factor receptor (HER2) was examined in ovarian cancer cells." (PMID 36879003, 2023). "In ovarian cancer, overexpressed STC2 promotes epithelial-mesenchymal transition, as manifested by the increase in N-cadherin/vimentin loose fibroblastic colonies and the mesenchymal marker expression, and the decrease in epithelial marker expression." (PMID 35719372, 2022). "In ovarian cancer cells, overexpressing of HK2 enhanced cell motility by inducing of EMT-related proteins, such as CDH2, fibronectin, MMP9, ZEB1, ZEB2 and vimentin." (PMID 35953860, 2022). "Compared with the shRNA-NC group, the expression of E-cadherin in ovarian cancer tissues after silencing UNC5B expression was upregulated, while expression of vimentin was downregulated." (PMID 35035481, 2022). "The expression of N-cadherin, vimentin, MMP2 and MMP9 was significantly reduced when ZNF252P-AS1 was inhibited in ovarian cancer cells, whereas E-cadherin was dramatically up-regulated." (PMID 34980214, 2022).
ovarian carcinoma (continued). "In summary, our results indicated that PARD6A affected EMT of ovarian cancer cells through SNAIL1 signaling pathways, which subsequently modulated the expression of VIMENTIN and E-cadherin." (PMID 35379775, 2022). "It was indicated that PARD6A affected EMT of ovarian cancer cells through SNAIL1 signaling pathway and subsequently modulated the expression of VIMENTIN and E-cadherin, which was further confirmed by knockdown and overexpression of SNAIL1 experiments." (PMID 35379775, 2022). "The EMT markers (E-cadherin, N-cadherin and Vimentin) and stemness markers (Nanog and OCT4) were analyzed from metastatic ovarian cancer tissues." (PMID 36231102, 2022). "Studies in epithelial ovarian cancer have shown the inactivation of STAT3 can reduce N‐cadherin and vimentin expression and suppress cell migration behavior." (PMID 34231329, 2021). "Consistently, KLF4 overexpression decreased levels of vimentin and Slug and increased those of E-cadherin in OVCAR3 ovarian cancer cells." (PMID 34680284, 2021). "Among which, elevation in the gain-of-function R248Q mutant p5326, cyclin D1 and β catenin, known to transcriptionally regulate cyclin D127, as well as vimentin which like β catenin is involved in EMT and ovarian cancer progression." (PMID 32728020, 2020). "In ovarian cancer, overexpression of TET1 increases chemoresistance partially through promoting epithelial-to-mesenchymal transition mediated by the induction of vimentin level." (PMID 32528872, 2020). "We found that vitamin C decreased vimentin expression and increased E-cadherin expression in ID8 tumor nodules, which indicated that vitamin C suppresses EMT in ovarian cancer cells in vivo." (PMID 32477126, 2020). "In ovarian cancer, miR-146b inhibited the expression of F-box and leucine-rich repeat protein 10 (FBXL10) and also upregulated Cyclin D1, vimentin (VIM), and zona-occludens-1 (ZO-1)." (PMID 31936634, 2020). "In ovarian cancer, a previous study revealed that miR-506 inhibited EMT and metastasis by regulating the expression of E-cad, vimentin and N-cad." (PMID 33336050, 2020). "Firstly, ovarian cancer tissue showed an increased protein expression of Notch1, Snail, MMP-2, N-cadherin and Vimentin, but had decreased expression of E-cadherin." (PMID 32547317, 2020). "EMT of ovarian cancer cells was also depicted by quantification of EMT‐related factors (E‐cadherin, N‐cadherin and vimentin) after LINC00176 expression was depleted by delivery of si‐LINC00176 or restored by oe‐LINC00176, respectively." (PMID 31668012, 2020). "Ovarian cancer tissue had increased expression of Notch1, Snail, MMP-2, N-cadherin and Vimentin, but had decreased expression of E-cadherin." (PMID 32547317, 2020). "The expression of the chemotherapy-induced upregulated EMT markers (VIM and Snail) and stem cell markers (CD44 and CD133) in ovarian cancer was also reserved by GLI1 knockdown." (PMID 32242101, 2020). "On the other hand, Huang and co-workers have shown that some ovarian carcinoma cell lines exhibit intermediate EMT states presenting low E-cadherin and high vimentin expression patterns." (PMID 32545405, 2020). "In contrast, the inhibition of SERPIND1 expression in ovarian cancer cells reduced the phosphorylation of PI3K/AKT, increased E-cadherin expression, and reduced the expressions of N-cadherin, Vimentin, MMP2, and MMP9." (PMID 31637210, 2019). "It has been reported that CD73 regulates other MSC markers, such as N-cadherin and vimentin, and their expression decreases following knockdown of CD73 in ovarian cancer-initiating cells." (PMID 30931957, 2019).
ovarian carcinoma (continued). "To further analyze the role of SERPIND1 in ovarian cancer cells, we examined the major proteins of epithelial–mesenchymal transition (EMT), including MMP2, MMP9, Vimentin, N-cadherin, and E-cadherin." (PMID 31637210, 2019). "The expression of snail and vimentin increased three times, while E-cadherin expression was almost halved after 48-h exposure of BPA in ovarian cancer cells." (PMID 29323181, 2018). "Examples include VCAN, VIM and IL32, mediators of cell motility and invasion when upregulated in ovarian cancers, HNSCCs and metastatic CRCs, respectively." (PMID 29228717, 2017). "The elevated expression of TGFβ1 in the CAF exosomes induced ovarian cancer cell EMT, which was accompanied by a notable decrease in E-cadherin and an increase in vimentin expression." (PMID 29221185, 2017). "In 20(S)-Rg3-treated SKOV3 and 3AO cells, epithelial marker E-cadherin was up-regulated, while mesenchymal markers N-cadherin and vimentin were down-regulated, indicating that 20(S)-Rg3 reversed EMT in SKOV3 and 3AO ovarian cancer cells." (PMID 28881818, 2017). "In our panel of ovarian cancer cell lines, NNMT protein expression positively correlated with expression of ZEB1 and other mesenchymal markers, such as vimentin." (PMID 28412735, 2017). "In this study we demonstrate that the elevation of Oct4A at the mRNA level correlates with the enhancement in TUBB2A, PLEC and VIM expression in parental HEY, SKOV3 and OVCAR5 ovarian cancer cell lines in response to paclitaxel or cisplatin treatments." (PMID 28406185, 2017). "Since CFG was able to functionally suppress ovarian cancer invasion and migration, we investigated the protein expression of EMT markers, such as E-cadherin, N-Cadherin, Vimentin, and Fibronectin." (PMID 28036353, 2016). "The authors also demonstrated that miR-506 simultaneously suppressed Vimentin and N-cadherin, and silencing of Vimentin reversed EMT and inhibited cell migration and invasion in epithelial ovarian cancer (EOC) cells." (PMID 27542202, 2016). "Cisplatin-induced EMT is correlated with reduced E-cadherin and increased vimentin, Snail, Twist, and matrix metalloproteinase (MMP)-2 expression in ovarian cancer cells." (PMID 25839165, 2015). "Consistent with the changes in the expression and localisation of N-cadherin, vimentin and β-catenin, EGF also induced a motile phenotype in ovarian cancer cells as evaluated by wound-healing assay in serum-free medium." (PMID 19088723, 2009). "Furthermore, its expression correlated with the mRNA levels of several stem-cell and EMT-related genes including LIN28, OCT4, VIM, and TGFB1 in the L1CAM+/CD133+ cell populations derived from ovarian cancer IGROV1 and SKOV3ip cells." (PMID 40429728, 2025). "In ovarian cancer cell line A2780, progranulin regulated the EMT-process through increased vimentin and Twist Family BHLH Transcription Factor 1 (Twist) expressions and also decreased the levels of E-cadherin and cytokeratin, thus promoting cell invasion and migration." (PMID 40566630, 2025). "Vimentin is an important protein that regulates EMT and cancer progression in ovarian cancer." (PMID 36902478, 2023). "In gefitinib-resistant ovarian cancer cells, A2780R and OVCAR-3R, 6-shogaol/gefitinib overcomes gefitinib resistance by inhibiting EMT phenomena such as the reduction in E-cadherin, and the increase in N-cadherin, vimentin, Slug, and Snail." (PMID 36768961, 2023). "C0 and C4 did not express ACTA2 or VIM, the marker genes for cancer-associated fibroblasts (CAFs), and expressed IFI6, which is associated with a malignant subpopulation in ovarian cancer, at a comparable level to other tumor clusters." (PMID 35892844, 2022). "In contrast, only a few of the CDC50A−Lin− cells (2.3%) were vimentin positive, suggesting that CDC50A+ cells are more mesenchymal-like and may participate in the dissemination and metastasis of ovarian cancers." (PMID 35982417, 2022).